INS (insulin)
Diseases named in the same sentence as INS in open-access papers (continued):
Sharing a sentence is not in itself a finding about the gene and the disease.
diabetes (continued). "I can't say that the donor who had diabetes maybe was better or worse, but likely, the donor who had diabetes may have also had hypertension and also had been on insulin for many years, and so on and so forth." (PMID 39780785, 2024). "The caregivers faced challenges in managing diabetic conditions, such as monitoring diet and blood glucose and administering insulin to children with diabetes, which in turn demonstrates the need for targeted education for diabetes management and care in schools." (PMID 39310630, 2024). "All patients with diabetes requiring insulin at baseline were on weekly cisplatin." (PMID 38392055, 2024). "Abnormal insulin secretion is necessary for the development of type 2 diabetes mellitus (T2DM)." (PMID 38975245, 2024). "This acquired form typically manifests as fat atrophy at the insulin injection sites, often accompanied by local fat hypertrophy, insulin resistance, and metabolic disturbances such as hypertriglyceridemia and dyslipidemia, which complicate the management of diabetes." (PMID 39759721, 2024). "There is evidence that the insulin-dependent release of AVP may be markedly dysregulated in diabetes mellitus and obesity." (PMID 38279313, 2024). "These include, in parallel with the neuropathological mechanisms observed in animal models of diabetes, antioxidants, anti-inflammatories, antidepressants, insulin itself, or oral antidiabetics, emphasizing proper glycemic control can prevent the neuropsychiatric complications of diabetes." (PMID 38279738, 2024). "Coetzee A. An introduction to insulin use in type 2 diabetes mellitus." (PMID 38572871, 2024). "This association was independent of body weight or insulin action, and was evident in patients without diabetes." (PMID 38206990, 2024). "Diabetes is a chronic metabolic disease and steadily increasing worldwide, characterized by abnormally high blood glucose levels, mainly resulting from inadequate insulin secretion or insulin resistance." (PMID 39845878, 2024). "A diabetes system built this way might be capable of eliciting the patient's thoughts and concerns about the difficulties of starting insulin." (PMID 38646041, 2024). "However, compared to people with T2DM, people with T1DM were more likely to adhere to a diabetes mellitus management plan that included insulin therapy and lifestyle modifications (73.7% vs. 26.3%, p=0.001)." (PMID 38298281, 2024). "By diminishing abdominal fat, cryolipolysis could play a role in improving insulin sensitivity, thereby contributing to diabetes management and prevention." (PMID 39337866, 2024). "It is believed that HRV is more related to insulin sensitivity than to the presence of diabetes." (PMID 38724937, 2024). "Including participants with diabetes would be important also because there are inconclusive indications that APOC3 inhibition could improve insulin sensitivity." (PMID 37972731, 2024). "In epidemiological studies, the presence of MASLD in adults with T1D was associated with poor blood glucose control together with other factors, such as age, duration of diabetes, modalities of subcutaneous insulin administration, and microvascular complications." (PMID 38498227, 2024). "Banting died in a plane crash on February 21, 1941, at the early age of 49, but the legacy of insulin continues to inspire ongoing research into diabetes treatment and management, reminding us of the profound impact that medical research can have on human health." (PMID 39691108, 2024). "An inverse relationship exists between insulin resistance and BMD, suggesting that in type 2 diabetes mellitus, insulin resistance might diminish the beneficial effects of insulin on bones." (PMID 38172731, 2024). "Time-dependent Cox proportional hazard models were fitted across all patient subgroups, with each Cox model adjusted for sex, age, duration of diabetes, current smoking, regular drinking, BMI, BP, HbA1c, serum cholesterol level, eGFR, and use of insulin in all other subgroup analyses." (PMID 38319705, 2024).
diabetes (continued). "HbA1c is an important diabetes marker of both postprandial and fasting glucose over several weeks, while fasting glucose is a marker of hepatic gluconeogenesis regulated by hepatic insulin sensitivity." (PMID 39273678, 2024). "Therefore, RIN-m5f cells have become a commonly used model for investigating the roles and mechanisms of insulin secretion in diabetes research." (PMID 39202492, 2024). "Taken together, our results suggest that skipping of MADD exon 30 may lead to diabetes by affecting both β cell function and peripheral insulin signaling." (PMID 38775154, 2024). "To determine whether the use of insulin among diabetes participants affects the production of anti-capsular IgG, we compared those using insulin with those not using insulin among diabetes individuals." (PMID 39121085, 2024). "In the EVEREST trial, no prognostic difference concerning diabetes-related therapeutic strategies (i.e., diet alone, oral treatment or insulin) with regard to the risk of all-cause mortality or HF-related hospitalization was observed." (PMID 38337436, 2024). "Type 1 Diabetes Mellitus (DM1) is a chronic condition characterized by the autoimmune destruction of insulin-secreted beta cells in the pancreas, severe insulin deficiency may result in chronic hyperglycemia with many complications." (PMID 39224588, 2024). "There is a scarcity of research that has correlated low endogenous insulin production measured by serum C-peptide level with poor glycaemic control with oral anti-diabetic drugs in patients with long-term type 2 diabetes mellitus in India (especially in Bihar)." (PMID 38654804, 2024). "Across questionnaires, commonly perceived omissions related to the impact of diabetes on mental / emotional health, and on finances, as well as the impact of diabetes management activities (e.g. insulin administration modality; diet; glucose monitoring) and extreme glucose levels on overall QoL." (PMID 39218951, 2024). "However, in this current study, the associations of androgenicity with development of MetS were independent from insulin levels, BMI level, diabetes medication use, and weight change." (PMID 38213908, 2024). "In addition, participants with chest pain were more likely to have higher total cholesterol, triglyceride, hemoglobin type A1C (HbA1C), fasting glucose, and insulin levels, a higher TyG index, and a greater incidence of diabetes and CVD." (PMID 38555461, 2024). "Insulin is one of the important means for controlling blood glucose in patients with diabetes." (PMID 38803476, 2024). "Among diabetic individuals with foot ulcers, there was a pronounced prevalence of insulin use (85%), indicating poorer diabetes control, whereas oral hypoglycemic agents appeared to be the popular medication within the non-DFU diabetic group (63.3%) (p < 0.01)." (PMID 38389641, 2024). "Here, we found that trimethylamine N-oxide (TMAO) at a similar concentration to that found in diabetes could directly decrease glucose-stimulated insulin secretion (GSIS) in MIN6 cells and primary islets from mice or humans." (PMID 38514666, 2024). "These nudges, comprising notifications or alerts from diabetes technologies like insulin pumps, continuous glucose monitors, and mobile apps, serve to notify individuals about various situations, such as high or low glucose levels, low battery of diabetes management devices, and low insulin storage." (PMID 38846748, 2024). "Our study also revealed that asprosin may contribute to the development of diabetes by regulating glucose homeostasis, insulin secretion, and insulin resistance." (PMID 39334889, 2024). "Specifically, among 142 participants with diabetes who reported using insulin in CARE, 101 had linked prescription claims data available for analysis; using these linked data, 81.2% (82/101) showed at least 1 claim for insulin." (PMID 38412008, 2024). "Only 16% of the population had insulin requiring diabetes mellitus." (PMID 38987835, 2024).
diabetes (continued). "Thus, our data showed a progressive decrease of diabetes duration, a higher rate of subjects with HbA1c < 7% and a reduction of those with HbA1c > 8%, among T2D subjects starting insulin therapy, when comparing the last vs. the first quinquennium." (PMID 38441838, 2024). "Similarly, in vivo studies based on rodents have shown reduced hepatic GHR expression and GH binding following induction of diabetes, and that insulin treatment facilitated GH binding." (PMID 39665021, 2024). "Age, triglycerides (TG), UA, glycosylated hemoglobin (GHB), insulin, tobacco use, WC, BMI, hypertension, diabetes mellitus, TyG index, TyG-BMI index, and HOMA-IR were statistically significantly higher in the gout group than in the no-gout group (all P < 0.001)." (PMID 38745171, 2024). "Myricetin may enhance insulin sensitivity, shield pancreatic beta cells from damage, and avert diabetes-related complications by lowering oxidative stress and inflammation." (PMID 38465169, 2024). "Substantial evidence indicates that insulin-vasopressin interactions may be significantly altered in obesity and diabetes mellitus." (PMID 39769071, 2024). "In the prospective Cardiovascular Health Study of over 4000 older American adults, TMAO level was associated with fasting insulin level but not insulin sensitivity or risk of type 2 diabetes mellitus." (PMID 39408044, 2024). "For example, diabetes is suppressed with administration of a plasmid encoding ChgA, IGRP, GAD65 and insulin antigens, and targeting DβH233-241, ZnT8158-166, ZnT8282-290 and proinsulin with a plasmid approach provides better disease protection than proinsulin alone." (PMID 39211046, 2024). "Furthermore, CRP >10 mg/L, age, duration of diabetes, Wagner grades 3–5, with cardiovascular disease (CVD), and using insulin were identified as risk factors for malnutrition in diabetic patients." (PMID 39364802, 2024). "Insulin was not included due to potential risk of bias related to advanced diabetes and the associated confounding by indication." (PMID 39835258, 2024). "He received diabetes counseling and insulin teaching from the diabetes nurse educator." (PMID 39726058, 2024). "Given what is known about MGLL function, it could be a potentially interesting target for the controlling of adipogenesis and has implications to insulin sensitivity in diabetes." (PMID 39595019, 2024). "There may also be reduced diabetes self-management capacity leading to the need for third-party administration of insulin therapy in hospital, increasing risks for error." (PMID 39666732, 2024). "Somogyi is best known for his hypothesis that excessive insulin treatment could destabilize diabetes." (PMID 39718705, 2024). "At high doses, streptozotocin causes abrupt, large-scale β-cell death and insulin-deficient diabetes within 4–5 days, without requirement for any auto-immunity." (PMID 39769216, 2024). "The study suggested that patients with diabetes mellitus could benefit from treatment with carvedilol due to decreased insulin resistance." (PMID 39759452, 2024). "Aberrant endo-lysosomal function could exacerbate the cellular stress response, influencing insulin signaling pathways and glucose metabolism during diabetes." (PMID 38715799, 2024). "Diabetes mellitus (DM), a chronic condition brought on by a lack of insulin, a defect in how insulin works, or both, causes delayed hyperglycemia, which in turn affects the body's metabolic functions." (PMID 39055230, 2024). "Despite this, PMI values were significantly higher in the insulin group than the oral antidiabetic group, indicating that insulin therapy reduces sarcopenia risk regardless of diabetes duration." (PMID 39058051, 2024). "Conventional diabetes treatments such as lifestyle modification, insulin or secretagogues, and insulin sensitizers are insufficient for achieving adequate glycemic control in most RMS patients, and their extreme insulin resistance limits the efficacy of high-dose insulin." (PMID 38957655, 2024).
diabetes (continued). "Insulin therapy remains a cornerstone of diabetes management." (PMID 39734941, 2024). "Recently, it has been suggested that several miRNAs, which mainly regulate the insulin signaling pathway, may be involved in the pathogenesis of both diabetes and cancer." (PMID 38935200, 2024). "Ewald’s multiple linear regression analysis showed that urine glucose excretion, plasma glucose concentration, glycated hemoglobin, serum triglyceride and total cholesterol concentrations, diabetes duration, and insulin dose per kg body weight explained 54% of the variation in vascular reactivity." (PMID 38790982, 2024). "Insulin requirements then increase, which can lead to the development of ketoacidosis." (PMID 39519429, 2024). "mTOR activation may enhance β-cell proliferation and insulin secretion with subsequent reduction in glycemia, thus protecting against diabetes." (PMID 39201476, 2024). "Overall, the risk factors for DFU are multifaceted and include aspects such as age, rural living, income, medical history, insulin use, diabetes complications, peripheral neuropathy, vascular disease, poor glycemic control, and certain lifestyle factors like smoking." (PMID 38758936, 2024). "A study found that selenium supplementation could improve insulin sensitivity and lower blood glucose levels in patients with diabetes." (PMID 39839287, 2024). "These compounds have been shown to enhance insulin secretion, regulate blood sugar levels, and may help prevent diabetes-related complications by influencing complex molecular processes." (PMID 39458444, 2024). "Oleanolic acid alleviates diabetes and metabolic syndrome by improving insulin sensitivity." (PMID 39063310, 2024). "Insulin resistance (IR), characterized by diminished sensitivity or responsiveness to insulin, is implicated in the etiology of numerous disorders, including non-alcoholic fatty liver disease (NAFLD), diabetes mellitus (DM), cardiovascular disease (CVD), and cognitive impairment." (PMID 38773587, 2024). "Furthermore, EOs have potential hypoglycemic benefits attributed to their capacity to increase glucose uptake, reduce glucose production, and enhance insulin sensitivity in diabetes." (PMID 38279251, 2024). "For individuals with diabetes or prediabetes, physical activity is shown to reduce glycosylated hemoglobin (HbA1C) levels, decrease insulin resistance, decrease lipid levels, increase insulin sensitivity, and improve blood pressure." (PMID 39712722, 2024). "NICE guidelines on the management of diabetes in pregnancy indicate that rtCGM should be considered in pregnant women with insulin-treated type 2 diabetes if they have problematic severe hypoglycaemia or unstable blood glucose levels causing concern despite efforts to optimise plasma glucose." (PMID 38951212, 2024). "Insulin-producing pancreatic β-cells have a central role in diabetes pathophysiology." (PMID 39159974, 2024). "Several articles also discovered that Diabetes mellitus could affect bone healing because insulin is considered a key molecule in bone metabolism and growth after spinal fusion." (PMID 38397978, 2024). "In diabetes, the upsurge of insulin demand induces ER stress in the secretory pancreatic β-cells." (PMID 39684919, 2024). "Pioglitazone is used to reduce insulin sensitivity in diabetes." (PMID 39062500, 2024). "Given the potent effect of insulin, it is conceivable that systemic insulin treatment may reduce the incidence of glaucoma in patients with diabetes; however, robust and well-controlled studies showing this association are lacking." (PMID 39110798, 2024). "Bariatric surgeries do not cause diabetes, rather, they are used in diabetic animals by investigators to study the effects of weight reduction on improving insulin sensitivity and glucose metabolism." (PMID 38444587, 2024). "The mechanisms by which insulin decreased oxidative stress could reduce hyperglycemia, which altered abnormal metabolic processes in diabetes." (PMID 38961333, 2024).
diabetes (continued). "However, a stable clinical status was ultimately achieved upon the introduction of methotrexate, concomitant with insulin therapy for diabetes and the implementation of a gluten-free diet for celiac disease." (PMID 39845887, 2024). "However, when they are unable to meet the body’s demand for insulin because of genetic defects and/or exogenous insults, diabetes mellitus ensues." (PMID 38533089, 2024). "Type 2 diabetes mellitus (T2DM) is a chronic metabolic disease featuring persistent elevated blood glucose levels (hyperglycemia) resulting from impaired insulin secretion or resistance to peripheral actions of insulin in target tissues." (PMID 39767255, 2024). "These include fasting, low preoperative fasting glucose, diabetes for more than 10 years, low body mass index (BMI), use of sulfonylureas and other insulin secretagogues, previous episodes of hypoglycaemia, advanced age, preoperative administration of subcutaneous insulin and prolonged surgery." (PMID 39512161, 2024). "Due to their potential effects on protein structure and function and, eventually, cellular processes involved in glucose metabolism and insulin signalling, deleterious single nucleotide polymorphisms (SNPs) in the OGT gene may have a major impact on diabetes." (PMID 38539217, 2024). "In addition, individuals with this atypical form of diabetes are able to discontinue insulin therapy within 4–12 weeks following the index episode of DKA and maintain excellent, long-term glycemic control on treatment with oral agents alone." (PMID 38765897, 2024). "Interestingly, hemodialysis has also been found to temporarily enhance insulin sensitivity in individuals with diabetes." (PMID 38904033, 2024). "Additionally, GLP-1 inhibits appetite, promotes satiety, delays gastric emptying, improves insulin sensitivity, stimulates beta-cell regeneration, and prevents beta cell apoptosis, making it a promising target for diabetes and obesity treatment." (PMID 39200346, 2024). "Earlier analyses by some of the authors of the study reported herein estimated the cost of manufacturing certain diabetes medicines, including insulins, finding that estimated cost-based prices were far below the market prices for insulin analogues at the time." (PMID 38536176, 2024). "Excessive excretion of minerals, including magnesium, potassium, and calcium, may further aggravate metabolic disturbances, insulin resistance, and the development of diabetes-related complications." (PMID 39839287, 2024). "In summary, taurine has a minimal influence on insulin sensitization in individuals with minor metabolic disorders (such as being overweight), but exerts a more pronounced effect in those with severe insulin resistance (such as obesity or diabetes)." (PMID 39796489, 2024). "AI and automated insulin delivery systems are transforming diabetes care." (PMID 39238969, 2024). "Given the widespread utilization of phthalates, prior research has extensively delved into examining the relationship between phthalates and various health outcomes, including serum insulin, type 2 diabetes mellitus, overweight, obesity, and skeletal abnormalities." (PMID 38903577, 2024). "In patients undergoing RSG, those without the A allele experienced better anthropometric and insulin level improvements, reducing diabetes risk after 12 months." (PMID 39125390, 2024). "This fact may indicate the need to repeat patient training, including in a diabetes school, and also is a basis to consider prescribing insulin pump therapy." (PMID 39896151, 2024). "The authors of this study proposed that a decrease in the SM pool in diabetes might lead to increased oxidative stress and decreased insulin secretion, resulting in hyperglycemia." (PMID 39519451, 2024).